CTRB2 (chymotrypsinogen B2)
Tractability: Small molecule: a high-quality ligand is known. Antibody: its Gene Ontology location is reachable by antibodies, with high confidence; UniProt places it where antibodies can reach, with medium confidence; UniProt predicts a signal peptide or a membrane-spanning region. PROTAC: a small molecule that binds it is known.
Gene: Protein-coding gene on chromosome 16 (75,204,103 to 75,207,161, reverse strand). Ensembl gene ENSG00000168928.
Subcellular location: Secreted, extracellular space
Pathways (Reactome):
Extracellular matrix organization: Activation of Matrix Metalloproteinases
Metabolism: Uptake of dietary cobalamins into enterocytes
Gene Ontology:
Molecular function: serine-type endopeptidase activity
Biological process: proteolysis
Cellular component: extracellular region
Genetic constraint (gnomAD): Loss-of-function variants: 2 observed, 5.36 expected, observed/expected ratio (o/e) 0.37, 90% interval 0.15 to 1.17. That is too few expected variants to judge how well the gene tolerates losing a copy. Missense variants: 155 observed, 121.37 expected, observed/expected ratio (o/e) 1.28, 90% interval 1.12 to 1.46. Synonymous variants: 73 observed, 50.92 expected, observed/expected ratio (o/e) 1.43, 90% interval 1.19 to 1.74.
Homologues: Orthologues: mouse Ctrb1 (85% identical), rat Ctrb1 (82% identical), macaque CTRB2 (79% identical), zebrafish ctrb.2 (67% identical), zebrafish ctrb.1 (66% identical), tropical clawed frog ctrb1 (65% identical), chimpanzee CTRB2 (65% identical), zebrafish ctrb.3 (65% identical), Drosophila melanogaster CG11912 (32% identical). Paralogues in human: CTRB1 (96% identical), CTRC (41% identical).
Diseases named in the same sentence as CTRB2 in open-access papers:
CTRB2 is named in the same sentence as 10 diseases in open-access papers, as found by Europe PMC text mining. Sharing a sentence is not in itself a finding about the gene and the disease. The quoted sentences say what the papers report.
pancreatic cancer (6 papers, 2022 to 2026). "Interestingly, genes associated with pancreatic cancer such as MALAT1 (noncoding RNA), CTRB2 (serine protease), CST7 (cysteine peptidase inhibitor), and BTG1 (anti-proliferation factor) were picked in multiple topics." (PMID 36968070, 2023). "A few studies about proteomics showed downregulated CTRB2, CELA3A, and CTRC, in pancreatic cancer, similar to the results of our study." (PMID 40289610, 2025). "Therefore, further analyses are needed to clarify the role of the CTRB1-CTRB2 locus in pancreatic cancer risk, which could include pre-clinical assessment of CTRB1 and CTRB2 as potential anti-tumour agents as was previously conducted for pro-enzymes PRSS1 and Chymotrypsinogen A28." (PMID 38684708, 2024).
type 2 diabetes (2 papers, 2019 to 2024). "For the BCAR1/CTRB1/CTRB2 region, the scores were negatively correlated (r = − 0.20), consistent with studies showing that the G allele of the rs720877 SNP in this region is associated with increased risk of type 1 diabetes but with decreased risk of type 2 diabetes." (PMID 31438962, 2019).
autoimmune disease (1 paper, 2025). A disorder resulting from loss of function or tissue destruction of an organ or multiple organs, arising from humoral or cellular immune responses of the individual to their own tissue constituents. "All but four out of 26 red group signals (PRF1, CTRB2, MEG3 and RNLS) were associated with other autoimmune diseases found in the Open Targets Genetics portal." (PMID 39749473, 2025).
chronic pancreatitis (1 paper, 2025). A chronic inflammatory process causing damage and fibrosis of the pancreatic parenchyma. "This explains why the increased levels of CTRB2 in carriers of the CTRB1-CTRB2 inversion allele result in more efficient degradation of human anionic trypsinogen and protection against chronic pancreatitis." (PMID 40133496, 2025).
pancreatic ductal adenocarcinoma (1 paper, 2022). An infiltrating adenocarcinoma that arises from the epithelial cells of the pancreas. "GWAS have fine-mapped an intergenic variant near CTRB2 (rs72802342, CPP=0.66) that is associated with T2D, T1D, and pancreatic ductal adenocarcinoma (PDAC) and co-localizes with an accessible chromatin region in human acinar cells and islets." (PMID 36109769, 2022).
pancreatitis (1 paper, 2020). Inflammation of the pancreas. "Even though CTRB1 and CTRB2 together are the most abundant chymotrypsins in humans, there are no reported mutations in these proteases in association with pancreatitis." (PMID 32678161, 2020). "Furthermore, a frequently occurring inversion at the CTRB1-CTRB2 locus protects against pancreatitis by increasing CTRB2 expression resulting in more efficient trypsinogen degradation." (PMID 32678161, 2020). "Thus, relative to CTRC, the contribution of CTRB1 and CTRB2 to the chymotrypsin-dependent protection against pancreatitis in humans seems limited." (PMID 32678161, 2020).
cancer (3 papers, 2022 to 2026). A tumor composed of atypical neoplastic, often pleomorphic cells that invade other tissues. "Indeed, most of the patients’ tumor tissues contained REG1A- and CTRB2-positive cells, just around the cancer cells." (PMID 35165277, 2022).
tumor (3 papers, 2018 to 2024). "We found two genes, syncoilin (SYNC) and chymotrypsinogen B2 (CTRB2), to discriminate between tumor and non-tumor tissue in data set M1 (blue line)." (PMID 29675033, 2018).
CTRB2 also shares sentences with these, for which no sentence is quoted: Hyperglycemia (1 paper); type 1 diabetes (1).